ALB (albumin)
Diseases named in the same sentence as ALB in open-access papers (continued):
Sharing a sentence is not in itself a finding about the gene and the disease.
cardiac arrest (continued). "The SHAP showed that the top ten factors accounting for cardiac arrest in rescue-treated patients are prothrombin activity, platelets, hemoglobin, N-terminal pro-brain natriuretic peptide, neutrophils, prothrombin time, serum albumin, sodium, activated partial thromboplastin time, and potassium." (PMID 38057823, 2023). "We investigated whether combining the pre-arrest serum albumin level could improve the performance of the Good Outcome Following Attempted Resuscitation (GO-FAR) score for predicting neurologic outcomes in in-hospital cardiac arrest patients." (PMID 34017041, 2021). "The albumin solutions could have been administered just before cardiac arrests." (PMID 34017041, 2021). "Albumin level might also be a predictor of prognosis in cardiac arrest patients." (PMID 34007754, 2021). "We suggest that albumin level might be useful to predict mortality in patients with cardiac arrest." (PMID 34007754, 2021). "This study focused on the relationship between albumin levels at admission in the ICU and prognosis in patients with cardiac arrest." (PMID 34007754, 2021). "used this indicator to predict survival at 30-days in patients with in-hospital cardiac arrest and found that the prognostic performance of LAR was superior to that of a single measurement of lactate or albumin for predicting survival after in-hospital cardiac arrest." (PMID 38515077, 2024). "The combination of lactate as an expression for hypoxia and possibly the no-flow time after cardiac arrest and albumin as an expression for the status of the critically ill patient seems to have a predictive value for in-hospital mortality." (PMID 37373829, 2023). "Albumin infusion did not improve lactate clearance but was highly efficient to reduce fluid loading in a porcine model of post resuscitation syndrome after refractory cardiac arrest treated with VA-ECMO." (PMID 35729416, 2022).
Splenomegaly (33 papers, 2011 to 2026). Abnormal increased size of the spleen. "This may justify its use even in low-risk patients harboring one of the risk factors based on CRP and albumin, especially if splenomegaly is already present." (PMID 36900271, 2023). "The PC type, hepatomegaly and/or splenomegaly, Hb of ≤ 80 g/L, and albumin of ≤ 30 g/L were recently confirmed as independent prognostic factors for OS, especially in patients with iMCD." (PMID 37782352, 2023). "These patients frequently present a combination of persistent fever, elevated aminotransferase (AST, ALT), decreased serum albumin, jaundice, and hepatomegaly or splenomegaly." (PMID 37266439, 2023). "For OS, these included sex (p = 0.019), splenomegaly (p < 0.001), lymphocyte count (p = 0.014), aspartate transaminase (p = 0.038), albumin (p = 0.044), prothrombin time (p = 0.012), and alpha‐fetoprotein (AFP) (p = 0.015)." (PMID 35599583, 2022). "The duration time (years), splenomegaly, serum ALB and rs10118570 remained significant independent predictors of advanced fibrosis using univarite and multivariate analysis." (PMID 25153992, 2014). "Univariate and multivariate analysis in the discovery, replicative and combined studies, suggested that durations (years), splenomegaly, serum ALB and rs10118570 were independent predictors influencing the fibrogenesis." (PMID 25153992, 2014). "The HR for the duration time, splenomegaly, serum ALB and rs10118570 were 1.44 (P = 0.006), 1.54 (P = 0.014), 1.25 (P = 0.007) and 0.71 (P = 0.009), respectively." (PMID 25153992, 2014). "The JAK2 inhibitor ruxolitinib controls not only constitutional symptoms and splenomegaly, but also lowers CRP levels and increases albumin concentration." (PMID 36900271, 2023).
epilepsy (32 papers, 2010 to 2025). A brain disorder characterized by episodes of abnormally increased neuronal discharge resulting in transient episodes of sensory or motor neurological dysfunction, or psychic dysfunction. "The results indicated that advanced age (OR = 1.019, p = 0.007), higher NIHSS scores (OR = 1.074, p = 0.002) at admission, presence of epilepsy (OR = 2.641, p = 0.037), and elevated albumin levels (OR = 1.035, p = 0.009) at admission were associated with unfavorable functional outcomes." (PMID 40642210, 2025). "Blood–brain barrier (BBB) dysfunction is speculated to contribute to AD/MCI pathogenesis and is also considered a critical mechanism in epilepsy, where it is associated with albumin extravasation." (PMID 38999445, 2024). "Indeed, prominent albumin IR is observed in the brain parenchyma as early as 4 h after SE induction, preceding most of the epilepsy-associated histopathological alterations in our experimental model." (PMID 34025561, 2021). "Albumin-induced TGFβ signaling in astrocytes in turn provokes several physiological changes in these cells associated with the development of epilepsy, including excitatory synaptogenesis, impaired K+ and glutamate buffering, and production of pro-inflammatory cytokines." (PMID 34025561, 2021). "In addition, a high lipid profile and elevated hs-CRP levels were associated with a high urine albumin/creatinine ratio in patients with epilepsy." (PMID 29593629, 2018). "The blockade of TGFβ receptors has been shown to significantly reduce the incidence of albumin-induced epilepsy." (PMID 38389560, 2024). "Increased permeability of the BBB leading to extravasation of blood compounds like albumin and subsequent albumin-induced alterations in the brain parenchyma is considered to be a crucial factor for the development of epilepsy." (PMID 35812852, 2022). "For epilepsy, in addition to the epilepsy models involved in BBB breakdown and albumin extravasation, losartan has also been shown to attenuate seizure activity and neuronal damage in other models of epilepsy by different research groups." (PMID 35625943, 2022). "It has been reported that the systemic administration of pentylenetetrazol or kainic acid increases the infiltration of albumin into the brain in rabbit and rat models of epilepsy." (PMID 34959403, 2021). "In conclusion, these results show that 4 h after epilepsy induction, uptake of extravasated albumin by astrocytes is negligible." (PMID 34025561, 2021). "Immunohistochemical staining has also shown that albumin infiltrates into the brain in focal areas of epilepsy patients." (PMID 34959403, 2021). "A rodent epilepsy model induced by fluid percussion injury or albumin injection also exhibited down-regulation of Kir4.1 expression in regions related to seizure foci." (PMID 33424762, 2020). "The seizing brain with leaky BBB seems to promote predominantly neuronal albumin uptake, an observation requiring further investigation to define its role in epilepsy development." (PMID 29854942, 2018). "Serum levels of albumin are significantly elevated after BBB damage and can induce epilepsy by activating inflammatory cytokines, decreasing the epilepsy threshold, and causing gap junction coupling." (PMID 30258402, 2018). "In this study, we used two non-invasive parameters, OCT and urine albumin/creatinine ratio, to examine atherosclerotic microangiopathy in patients with epilepsy." (PMID 29593629, 2018). "BBB breakdown has been implicated both in the induction of seizures and in the progression to epilepsy with chronic seizure generation by exposure of neuronal cells to blood albumin and potassium ions." (PMID 20863362, 2010). "For instance, polyssorbate-80 coated albumin nanoparticles have been effectively utilized to target the delivery of levetiracetam, a widely used antiepileptic drug, enhancing its brain-specific delivery and thus optimizing the treatment of epilepsy." (PMID 38389560, 2024).
epilepsy (continued). "Animal studies have demonstrated that albumin extravasation in epilepsy is due to BBB breakdown." (PMID 35625943, 2022). "Notably, blocking TGF-β signaling with Alk5 inhibitors SJN2511 or SB431542, or with angiotensin receptor 2 antagonist losartan, prevents the albumin-initiated gene response and epilepsy." (PMID 35625943, 2022). "Supporting this hypothesis, blockade of TGF-beta signaling by losartan prevented seizures in an albumin-induced epilepsy model." (PMID 36233336, 2022). "Proinflammatory chemokines and cytokines released by astrocytes in epilepsy lead to blood-brain barrier dysfunction, followed by the albumin-mediated downregulation of GLT-1 through the transforming growth factor β pathway and eventually reduced glutamate astrocyte uptake." (PMID 36340784, 2022). "It is reported that serum albumin can extravasate from blood vessel into the brain parenchyma when the blood-brain barrier is dysfunctional, and this has been suggested to be involved in the pathogenesis of various types of epilepsy." (PMID 36341114, 2022). "The role of albumin in epilepsy has been demonstrated in infusion studies." (PMID 35625943, 2022). "In addition, the urine albumin/creatinine ratio was significantly increased in patients with epilepsy." (PMID 29593629, 2018). "Similar to its actions in epilepsy, it is possible that extravasated albumin can influence Kir4.1 expression in MS, and further dysregulation of Kir4.1 expression could facilitate the neurodegenerative process." (PMID 27067000, 2016). "Recently, astrocytes and albumin have been related to epilepsy, mainly through disruption of BBB." (PMID 24967376, 2014). "ALB antioxidant may be an add-on therapy for epilepsy treatment." (PMID 40217387, 2024). "Elevated levels of ALB before the administration of VPA are beneficial for the protection of lipids and reduction of dyslipidemic events in children with epilepsy." (PMID 38628642, 2024). "Therefore, supplementation of ALB may be a potential treatment strategy for epilepsy." (PMID 40217387, 2024). "The ratio of urine albumin to creatine and OCT findings showed that patients with epilepsy had higher abnormal microalbuminuria and narrowing retinal vein diameters, respectively." (PMID 29593629, 2018). "The infusion of albumin directly into the cerebral ventricles of naïve young rat results in a high incidence of this transient EEG abnormality, which is also observed in aged mice and models of AD and epilepsy." (PMID 35625943, 2022). "Disruption of the BBB accompanied by albumin extravasation occurs in human and experimental epilepsy, and there is growing evidence that this represents not only a pathological consequence but also a causative factor in epileptogenesis." (PMID 34025561, 2021). "Extravasated albumin was found also in brain tissue of human patients with chronic epilepsy, suggesting that BBB leakage might also play a role in epilepsy maintenance or progression." (PMID 29326952, 2017). "In addition, other blood-borne factors such as albumin could reinforce the iron-mediated pro-inflammatory gene expression we detected and act synergistically as a result of BBB compromise in epilepsy to activate glia." (PMID 34292399, 2021). "Strong albumin extravasation, but no astrocytic uptake, was detected 4 h after epilepsy induction." (PMID 34025561, 2021). "Serum albumin and uric acid levels were not significantly different in the patients from the control, but serum total bilirubin was significantly lower in the patients with newly diagnosed epilepsy than that of the controls (P <0.001)." (PMID 30026766, 2018). "Both the prevalence and incidence of seizure disorders is greater in MS patients than in the general population, but even without seizures, it is possible that leakage of albumin through a damaged BBB in MS could lead to some similar pathogenic events that occur in epilepsy." (PMID 27067000, 2016).
hypercoagulability (32 papers, 2017 to 2025). "A serum albumin <2.9 g/dL has been associated with increased hypercoagulability and thrombotic risk." (PMID 41246570, 2025). "Our results show that low serum albumin is associated with higher markers of chronic inflammation and hypercoagulation." (PMID 30515432, 2018). "Our findings indicate that low serum albumin is associated with inflammation and hypercoagulation over time in treated HIV infection." (PMID 30515432, 2018). "This hypercoagulability in canine CIE may be associated with albumin and antithrombin (AT) loss, although one study suggested that hypercoagulability was not correlated with the severity of decrease in these parameters." (PMID 40509037, 2025). "Additionally, circulatory instability caused by intravascular dehydration, low albumin levels in the CNS, and a hypercoagulable state are believed to have contributed to early circuit occlusion on multiple occasions." (PMID 41142893, 2025). "Moreover, hypercoagulability is linked to low serum albumin levels owing to greater levels of fibrinogen and factor VIII." (PMID 40283020, 2025). "Regular monitoring includes nutritional assessments (albumin, micronutrients), abdominal imaging, and thrombophilia reevaluation." (PMID 40602171, 2025). "Elevated inflammatory cytokines and acute-phase reactants contribute to hypercoagulability, while low serum albumin reflects both nutritional and inflammatory burden." (PMID 41156207, 2025). "Her low albumin can also contribute to a hypercoagulable state, further exacerbating her clinical and imaging findings." (PMID 40827175, 2025). "We have implicated neutrophils in extensive oxidative damage of circulating human serum albumin and in platelets activation and hypercoagulability, particularly in patients with poor mortality outcomes." (PMID 39834785, 2024). "Low albumin has been associated with higher fibrinogen and factor VIII levels, reflecting a hypercoagulable state." (PMID 38022097, 2023). "One study revealed that albumin supplementation is able to reduce hypercoagulability in SARS-CoV-2, which was confirmed by the observation of a marked reduction in D-dimers." (PMID 36077496, 2022). "Although multiple mechanisms have been involved in hypercoagulable state, the incidence of thromboembolism dramatically increases when serum albumin concentration is less than 2.0–2.5 g/dL, in human patients with PLN." (PMID 29386022, 2018). "Most likely, low levels of serum albumin, as observed in cancer patients, slightly shift the haemostatic system towards hypercoagulability, a prerequisite for the development of VTE." (PMID 28800610, 2017). "Unlike traditional scores such as Khorana and ThroLy, which rely heavily on tumor type and platelet count, the D-dimer/albumin ratio simultaneously captures hypercoagulability, inflammation, and nutritional status—three major contributors to thrombosis in hematologic malignancies." (PMID 41156207, 2025). "Clinical decision-making should incorporate a comprehensive assessment of patient-specific factors, including comorbidities (e.g., renal impairment, thrombophilia), pregnancy status, nutritional status (albumin <3.0 g/dl), and religious objections to plasma-derived products." (PMID 41179562, 2025). "Furthermore, patients with CRGNB infection appeared to be more prone to blood hypercoagulation and albumin depletion." (PMID 40521028, 2025). "The decrease in albumin not only leads to the decrease of immunoglobulin production and the decrease of immunity, but also aggravates blood volume insufficiency, tissue edema and hypercoagulability." (PMID 39144651, 2024). "This study provides the first evidence that oxidized albumin may be involved in hypercoagulability in patients infected with SARS-CoV-2." (PMID 36077496, 2022).
hypercoagulability (continued). "Lower serum albumin in controlled HIV is associated with higher markers of chronic inflammation and hypercoagulation, which could explain the prior observation that serum albumin predicts nonacquired immune deficiency syndrome events in HIV." (PMID 30515432, 2018). "Thus, the concomitant reduction in albumin along with the increase in LPS is a negative combination of factors that strongly contribute to enhanced thrombin generation and hypercoagulation and eventually higher thrombotic risk." (PMID 39456513, 2024). "Thus, low levels of albumin can also serve as a marker of a hypercoagulable state." (PMID 37653556, 2023). "Therefore, a low level of albumin can also serve as an indicator of hypercoagulable state." (PMID 35922845, 2022). "Moreover, hypercoagulability following albumin administration has been demonstrated in rabbits." (PMID 28800610, 2017). "It has been reported that low serum albumin can increase fibrinogen and factor VIII levels, resulting in a hypercoagulable state." (PMID 37772221, 2023). "Therefore, low serum albumin may be a marker of a hypercoagulable state." (PMID 35571156, 2022). "Previous studies have shown that CIE dogs exhibit hypercoagulability, as assessed by TEG, regardless of albumin, like in this study, or antithrombin levels." (PMID 40509037, 2025).